C5orf24 (chromosome 5 open reading frame 24)
Synonyms: FLJ37562
Tractability: PROTAC: UniProt records ubiquitination sites on it; ubiquitination databases record sites on it.
Gene: Protein-coding gene on chromosome 5 (134,845,680 to 134,859,735, forward strand). Ensembl gene ENSG00000181904.
Subcellular location (Human Protein Atlas): Nucleoplasm
Gene Ontology:
Molecular function: protein binding
Cellular component: nucleoplasm
Genetic constraint (gnomAD): Loss-of-function variants: 4 observed, 10.16 expected, observed/expected ratio (o/e) 0.39, 90% interval 0.19 to 0.9. The upper end of that interval is the gene's LOEUF score, 0.9, which puts it in group 3 of 6, group 1 being the genes least tolerant of losing a copy. Missense variants: 170 observed, 250.36 expected, observed/expected ratio (o/e) 0.68, 90% interval 0.6 to 0.77. Synonymous variants: 73 observed, 86.22 expected, observed/expected ratio (o/e) 0.85, 90% interval 0.7 to 1.03.
Homologues: Orthologues: macaque C6H5orf24 (100% identical), guinea pig C5orf24 (98% identical), dog C5orf24 (98% identical), pig C5orf24 (98% identical), mouse B230219D22Rik (94% identical), rat C17h5orf24 (91% identical), chimpanzee C5H5orf24 (78% identical), rabbit C5orf24 (76% identical), tropical clawed frog c3h5orf24 (70% identical), zebrafish si:ch1073-44g3.1 (54% identical), zebrafish C21H5orf24 (49% identical).
Diseases named in the same sentence as C5orf24 in open-access papers:
C5orf24 is named in the same sentence as 4 diseases in open-access papers, as found by Europe PMC text mining. Sharing a sentence is not in itself a finding about the gene and the disease. The quoted sentences say what the papers report.
leukemia (1 paper, 2023). A malignant (clonal) hematologic disorder, involving hematopoietic stem cells and characterized by the presence of primitive or atypical myeloid or lymphoid cells in the bone marrow and the blood. "Over-representation analysis shows the related GO terms for both ORF proteins in each pair: ‘GO:0016311~dephosphorylation’ and ‘GO:1903293~phosphatase complex’ (C2orf74 and C20orf27) as well as ‘PA444750~leukemia’ and ‘PA444761~ leukemia, myeloid’ (C5orf24 and C16orf71)." (PMID 37373333, 2023).
posttraumatic stress disorder (1 paper, 2021). "A study identified C5orf24 was upregulated in patients with posttraumatic stress disorder (PTSD) and high intrusion symptoms at baseline and downregulated in participants following treatment." (PMID 33897588, 2021).
cancer (1 paper, 2023). A tumor composed of atypical neoplastic, often pleomorphic cells that invade other tissues. "First, the subinteractomes of these ORF proteins contain proteins associated with ‘cancer hallmark’ and oncoproteins (e.g., the case of C5orf24 and its protein partners XPO1, PBX1, MYC, CIC, GOPC, CREB1 and STK11)." (PMID 37373333, 2023).
C5orf24 also shares sentences with these, for which no sentence is quoted: thymoma (1 paper).